BRCA1 (BRCA1 DNA repair associated)
Diseases named in the same sentence as BRCA1 in open-access papers (continued):
Sharing a sentence is not in itself a finding about the gene and the disease.
tumor (continued). "Functional loss of BRCA1/2 and biomarkers including PALB2, FANCF, RAD54, PTEN, EMSY, XRCC2, XRCC3 in tumour biopsy specimens could potentially also have predictive value for PARP inhibition and need to be prospectively investigated in clinical trials." (PMID 21989215, 2011). "Indeed BRCA1 acts mainly as a tumor suppressor through transcriptionally regulating genes involved with DNA repair." (PMID 24212667, 2011). "The lack of association between expression of BRCA1 and these tumour characteristics warrants further investigation with a larger number of samples." (PMID 23508738, 2011). "Such inhibitors might actually stimulate HRR and lead to cell-cycle arrest with relatively little impact on the radiosurvival of tumor cells with normal BRCA1." (PMID 21666281, 2011). "That is, despite the expected differences in the frequency of tumor types between the two sets of carriers, heterogeneity was observed in the distribution of rs299290 genotypes in BRCA1, but not BRCA2, mutation carriers." (PMID 22110403, 2011). "Given the common role of NRF-1 and GABP in regulating mitochondrial function, the NRF-1 > GABPβ > BRCA1 pathway suggests a link between tumour initiation via disruption of stem cell maturation and the abnormal mitochondrial metabolism (Warburg effect) that has long been observed in tumours." (PMID 21609478, 2011). "Firstly, deregulation of many proteins such as deficiency of myosin light-chain phosphorylation, overexpression of Aurora A, and mutation/inactivation of many tumor suppressers such as APC, BRCA1, and LATS2 could induce tetraploid cells." (PMID 22076149, 2011). "The findings of this study may be important in the future design of clinical trials involving HDAC inhibitors using BRCA1 as a tumour biomarker." (PMID 21854619, 2011). "We should consider that BRCA1 is a large protein with multiple functional domains that interact directly or indirectly with a variety of molecules through which BRCA1 maintains genome integrity and represses tumor formation." (PMID 21483040, 2011). "We performed further BRCA1 mutation screening on DNA samples from the women whose tumours had mitotic indices over 50 per 10 h.p.f. and a trabecular growth pattern and who were not already known to carry a mutation in BRCA1 (n=37)." (PMID 21343941, 2011). "BRCA1 is a well-characterized tumor suppressor gene which codes for proteins that have important roles in the regulation of the cell cycle and in the apoptosis of tumor cells." (PMID 21985575, 2011). "Thirteen tumours showed low BRCA1 gene expression measured by qRT-PCR." (PMID 22032731, 2011). "BRCA1 encodes a tumor suppressor protein that acts as a negative regulator of tumor growth and is involved in DNA-damage repair." (PMID 22016618, 2011). "Compared with the risks when the ER status of the tumour is unknown, the BRCA1 carrier probabilities are higher at all ages when the tumour is known to be ER-negative, and are lower when the tumour is known to be ER-positive." (PMID 20482762, 2010). "This percentage was significantly higher for the gains of the BRCA1-mutated tumor group but not for the BRCA2-mutated tumor group when compared to the sporadic control tumors (p = 2.5 × 10-3 calculated with t-test with unequal variance)." (PMID 20735817, 2010). "In the case of BRCA1, this may reflect the confounding effect of the presence of normal cells in these samples, which do have BRCA1 mRNA, even though the tumor cells may lack expression." (PMID 20843305, 2010). "These sporadic tumours behave like BRCA1 and BRCA2 deficient tumours but do not possess germ line mutations in either gene." (PMID 24281034, 2010). "HER2-positive tumours have been shown less common in both BRCA1 and BRCA2 mutation carriers than in noncarriers." (PMID 20482762, 2010). "Previous reports in MZ twins with BRCA1 and BRCA2 mutations suggest that an analogous regulated program may also occur in other kinds of hereditary tumours." (PMID 20687928, 2010).
tumor (continued). "Contingency table analyses demonstrate significant differences in the EC tumor response rate between BRCA1-positive and BRCA1-negative baseline foci groups and between Rad51-positive and Rad51-negative EC-induced foci groups for all three criteria of the response rate (ZIO 65%, ZIO 50%, RECIST)." (PMID 20205718, 2010). "Conversely tumours in BRCA1 mutation-carriers are more likely to be ER-negative than tumours in non-carriers." (PMID 20146796, 2010). "In our control group tumor size was slightly larger than in the BRCA1 related group." (PMID 20398395, 2010). "Furthermore, since BRCA1-related tumours are more likely to be triple negative, the greatest advantage was shown for ER-negative breast cancer, were chemotherapy is the most active." (PMID 20219108, 2010). "The analysis correlating focus formation of BRCA1, γH2AX, and Rad51 prior to treatment and of Rad51 foci after EC treatment with the mean tumor volume reduction or tumor response rate uncovers a significant inverse correlation with tumor response for each of the four conditions." (PMID 20205718, 2010). "Finally, in 41 patients for whom sufficient tumor tissue was available, intratumoral BRCA1 mRNA levels were assessed by RT-QPCR." (PMID 20209131, 2010). "Importantly, tumor-associated mutation in the RING-finger domain of BRCA1 abolishes the ubiquitin ligase activity of the BRCA1/BARD1 complex, suggesting a strong connection between BRCA1's E3 ligase activity and its tumor suppressor function." (PMID 21217819, 2010). "Incorporating information on tumour pathology influences the predicted probabilities of carrying a BRCA1 or BRCA2 mutation, in particular BRCA1, and may therefore have implications for genetic testing and clinical decision-making." (PMID 20482762, 2010). "One potential mechanism of retaining elevated HIF-1α in both BRCA1 and basal-like may be the relative paucity of PHD3, which showed significantly lower expression in BRCA1 tumours." (PMID 19724277, 2009). "One of the still unexplained features of BRCA1-mutant breast tumours is their frequent lack of ER expression; in fact, up to 90% of these tumours exhibit a loss of ER expression." (PMID 19818148, 2009). "Given the common roles of the BRCA gene products in genomic maintenance, this suggests that phenotypic differences between BRCA1- and BRCA2-associated tumours impose selective advantages for distinct genomic alterations in the context of instability generated by BRCA-deficiency." (PMID 19589159, 2009). "Our data are in keeping with previous findings, indicating the presence of epigenome defects as a common feature of tumor cells, rather than a unique association between BRCA1 and global heterochromatin maintenance." (PMID 19440381, 2009). "Indeed, this feature characterized both familial and sporadic tumours displaying BRCA1- or BRCA2-like spectrums of genomic alterations." (PMID 19589159, 2009). "In summary, in this study we have established the gene expression profiling of a series of BRCA1 tumours and found that there is a further degree of heterogeneity beyond the main classification by the expression of ESR1 and the presence or absence of a basal-like phenotype." (PMID 19826428, 2009). "In contrast, three of the five BRCA1 ESR1-negative tumours, which showed the highest levels of NFκB2 and RELB expression, harboured missense mutations that might led to an aberrant but still present BRCA1 protein." (PMID 19826428, 2009). "BRCA1-associated tumours have a high probability of being ER negative (up to 90%), PR negative (79%) and with a low frequency of HER2 expression." (PMID 19818148, 2009).
tumor (continued). "Our findings suggest the aggressive nature of BRCA1, basal-type tumours may be partly explained by an enhanced hypoxic drive and hypoxia-driven ER degradation, due to suppressed PHD and aberrantly located FIH expression." (PMID 19724277, 2009). "Interestingly, 1 OC patient from Krasnodar carried both BRCA1 5382insC and NBS1 657del5 mutation; tumor tissue from this woman demonstrated loss of heterozygosity of the wild-type NBS1 allele, but intact status of BRCA1 gene." (PMID 19338682, 2009). "Another common deletion is in the region of BRCA1, a known tumor suppressor gene." (PMID 19352461, 2009). "Two of the 31 most differentially expressed genes between the ESR1-negative and ESR1-positive BRCA1 tumours, CD133 and MMP7, were evaluated by immunohistochemistry and immunofluorescence in an independent series of 15 BRCA1 tumours, previously classified as basal or luminal." (PMID 19826428, 2009). "We found two tumours within this genomic subgroup displaying loss of BRCA1 expression without promoter methylation of the BRCA1 gene and both of these tumours expressed the basal marker CK5/6." (PMID 19589159, 2009). "However, tumor tissue from the BRCA1/NBS1 heterozygous carrier from our OC group contained biallelic inactivation of NBS1 but not BRCA1." (PMID 19338682, 2009). "Most BRCA1-associated tumours show loss of heterozygosity (LOH) at the BRCA1 locus, leading to loss of the wild-type allele, which is consistent with a tumour suppressor function of BRCA1." (PMID 19904273, 2009). "Tumours with the highest cyclin B1 expression (>10%) were more frequent among BRCA1 than sporadic (OR 2.8, 95% CI 1.4–5.6, P=0.003) or familial BRCA1/2 mutation negative (OR 4.8, 95% CI 2.3–9.9, P<0.0005) patients." (PMID 19293801, 2009). "This hormone dependency might also be the reason why BRCA1 specifically functions as a tumour suppressor in hormone-sensitive tissues such as breast and ovaries." (PMID 19904273, 2009). "Finally high BRCA1 mRNA tumor carriers had a better survival if treated with taxanes even if statistical significance was not reached." (PMID 19825178, 2009). "Importantly, we show that the development of a subset of sporadic tumours is similar to that of either familial BRCA1- or BRCA2 tumours." (PMID 19589159, 2009). "Estimations show that the probability of being a BRCA1-mutation carrier in a woman with FBC diagnosed before the age of 35 years with a grade 3 tumour and ER negative status is 25%." (PMID 19818148, 2009). "This suggests a similar mechanism by which these tumours acquire instability and we propose here that this might relate to the involvement of the BRCA1 and BRCA2 genes in error-free DNA repair of double-strand breaks through HR (homologous recombination)." (PMID 19589159, 2009). "The importance of establishing a simple and effective classification scheme to identify such tumours lies in the potential benefit of targeted therapy (PARP inhibitors, platinum drugs) for a much larger group of patients than the relatively few BRCA1 and BRCA2 germline mutation carriers." (PMID 19589159, 2009). "Although the immune response gene-set is differentially expressed in the same direction in all ESR1-negative BRCA1 tumours examined here, it can stratify tumours in at least two additional subclasses depending on the magnitude of the expression of specific genes." (PMID 19826428, 2009). "In addition, in BRCA1 depleted normal and tumor cells and in BRCA1 reconstituted cells, the BRCA1 status did not closely correlate with XIST localization." (PMID 19440381, 2009). "It is not yet known whether there are differences in the molecular or clinical characteristics within BRCA1 or between BRCA1 and sporadic basal-like tumours." (PMID 19826428, 2009). "The aggressive nature of BRCA1 and basal-type tumours may be partly explained by an enhanced hypoxic drive and hypoxia driven ER degradation because of suppressed PHD and aberrantly located FIH expression." (PMID 19724277, 2009).
tumor (continued). "In addition to the major classification mediated by ESR1 or basal markers, this study reveals further complexity of BRCA1 tumours." (PMID 19826428, 2009). "Translocation of FIH into the cytoplasm may be a mechanism by which BRCA1 and basal-type tumours escape inhibition of HIF-1α activity." (PMID 19724277, 2009). "Furthermore, BRCA1 tumours show a so-called ‘triple negative’ phenotype being oestrogen receptor (ER), progesterone receptor (PgR) and HER2 negative." (PMID 19724277, 2009). "BRCA1 tumours correlated with positivity for HIF-1α (P=0.008) and negativity for PHD3 (P=0.037)." (PMID 19724277, 2009). "However, using Brca1 mouse mammary models for preclinical development has been limited due to complicated breeding schemes, variable penetrance, and prolonged latency of tumor development." (PMID 18394172, 2008). "BRCA1-associated tumours are usually negative by immunohistochemistry for the oestrogen receptor (ER), the progesterone receptor (PR) and HER2." (PMID 18269736, 2008). "Studies of tumor biology and development of novel therapies for tumors associated with BRCA1 deficiency are hampered by the lack of readily available material for in vitro and in vivo studies." (PMID 18394172, 2008). "Nine samples (18%) were found to have loss of BRCA1 due to epigenetic events; these samples all had hypermethylation of the BRCA1 promoter accompanied by decreased BRCA1 mRNA levels (relative qRT-PCR expression <0.7) and/or lack (less than 1% of tumour nuclei) of BRCA1 immunohistochemical staining." (PMID 18208621, 2008). "The first grouping labels the 22 tumor samples according to BRCA1 mutation status (positive or negative), and the second grouping labels the samples according to BRCA2 mutation status (positive or negative)." (PMID 18554411, 2008). "It should also be noted that these women were unselected for BRCA1-like features and that the BRCA1 methylation status of their tumours was unknown." (PMID 18269736, 2008). "One factor that may affect this is the strong association of CK-5/6 with age at diagnosis, because the tumours included in our study were unselected for age and about 35% of the BRCA1 tumours in our study were diagnosed at age 50 years or older." (PMID 18275599, 2008). "Tumour data contributed considerably to this classification, with the presence of basal cytokeratin markers and the absence of ER staining consistent with the tumour phenotype of a defective BRCA1 gene." (PMID 18036263, 2007). "This difference may reflect diverse biological behavior and pathways of tumor development among the older and the younger BRCA1 and BRCA2 patients, with impact also on prognosis and survival." (PMID 18053234, 2007). "Of these nine tumours, all but two had AI at the BRCA1 locus." (PMID 16846527, 2006).
tumor (continued). "According to this definition, 37.4% (49/131) of informative tumours had AI at the BRCA1 locus." (PMID 16846527, 2006). "BRCA1 protein expression was estimated in all BRCA1 methylated tumours by immunostaining." (PMID 16846527, 2006). "Of these four tumours, AI at the BRCA1 locus was detected in one case." (PMID 16846527, 2006). "Of all the 13 BRCA1 methylated tumours, seven were of grade 3, five of grade 2 and one of grade 1." (PMID 16846527, 2006). "We hypothesized that the failure of the mutant BRCA1 protein to affect E2-mediated DNA repair might have been due to decreased ability of the truncated tumor suppressor to interact with CBP." (PMID 16417649, 2006). "Similarly, a comparative genomic hybridisation study has reported a specific pattern of genetic alterations to be predictive of familial BRCA1 tumours and BRCA1 methylated tumours." (PMID 16846527, 2006). "It has previously been suggested that BRCA1 methylated tumours might phenocopy familial BRCA1 tumours." (PMID 16846527, 2006). "Interestingly, gene expression profiling has revealed similarities between BRCA1 methylated and familial BRCA1 tumours." (PMID 16846527, 2006). "Four tumours were estimated to have class 2 or 3 BRCA1 protein expression." (PMID 16846527, 2006). "BRCA1 gene copy number was determined in the BRCA1 methylated tumours by FISH analysis." (PMID 16846527, 2006). "However, tumours from the older patients in BRCA1 families differed significantly only in grade from tumours in non-BRCA1/2 patients." (PMID 15987451, 2005). "HER2 amplification is extremely rare in tumours associated with germline mutations of BRCA-1, which correlates well with the absent or sparse amounts of DCIS typically seen." (PMID 15700031, 2005). "However, in multivariate analysis the independent factors compared with non-BRCA1/2 tumours were age, grade and PgR negativity." (PMID 15642173, 2005). "In this study, we have evaluated whether tumour histology and immunohistochemistry are influenced by age of onset (menopause status) among families with BRCA1, BRCA2, or non-BRCA1/2 tumours." (PMID 15987451, 2005). "However, in multivariate analysis the independent factors, as compared with non-BRCA1/2 tumours, were age of diagnosis, grade, and PR-negativity." (PMID 15987451, 2005). "However, tumours of BRCA2 carrier patients diagnosed at 50 years or older had more distinctive features, and were more ER- and PR-, than tumours of younger patients or tumours of the same age group of BRCA1 patients or non-BRCA1/2 patients." (PMID 15987451, 2005). "This difference may reflect different biological behaviour and pathways of tumour development among the older and the younger BRCA1 and BRCA2 patients, with impact also on prognosis and survival." (PMID 15987451, 2005). "Tumours from the older BRCA1 patients resemble more those among the mutation-negative families, or sporadic tumours." (PMID 15987451, 2005). "Recently, cDNA expression analyses have suggested a basal epithelial phenotype for BRCA1 tumours." (PMID 15642173, 2005). "The findings here provide further information specifically with respect to older BRCA1 and BRCA2 patients and warrant further studies for evaluating the probability of mutation by combining information on family history and tumour characteristics in the various age groups." (PMID 15987451, 2005). "BRCA1 is a tumor suppressor gene mapped to position q21 of chromosome 17." (PMID 16389418, 2005). "The specific features of BRCA1-associated tumours among the younger age group, and lack of such features among the BRCA2-associated tumours, are consistent with the overall characteristics reported previously among BRCA1 and BRCA2 patients." (PMID 15987451, 2005).